MCM3 (minichromosome maintenance complex component 3)
Description:
Acts as a component of the MCM2-7 complex (MCM complex) which is the replicative helicase essential for 'once per cell cycle' DNA replication initiation and elongation in eukaryotic cells. Core component of CDC45-MCM-GINS (CMG) helicase, the molecular machine that unwinds template DNA during replication, and around which the replisome is built. The active ATPase sites in the MCM2-7 ring are formed through the interaction surfaces of two neighboring subunits such that a critical structure of a conserved arginine finger motif is provided in trans relative to the ATP-binding site of the Walker A box of the adjacent subunit. The six ATPase active sites, however, are likely to contribute differentially to the complex helicase activity. Required for the entry in S phase and for cell division (Probable).
Synonyms: HCC5; P1-MCM3; P1.h; RLFB
Tractability: Small molecule: a structure with a bound ligand is known. PROTAC: ubiquitination databases record sites on it; its protein half-life has been measured.
Target class: Enzyme; Hydrolase
Gene: Protein-coding gene on chromosome 6 (52,264,011 to 52,284,881, reverse strand). Ensembl gene ENSG00000112118.
Subcellular location: Nucleus; Chromosome
Subcellular location (Human Protein Atlas): Nucleoplasm
Pathways (Reactome):
DNA Replication: Activation of the pre-replicative complex; Assembly of the pre-replicative complex; Orc1 removal from chromatin; Switching of origins to a post-replicative state; Unwinding of DNA
Cell Cycle: Activation of ATR in response to replication stress
Gene Ontology:
Molecular function: ATP hydrolysis activity; protein binding; DNA binding; single-stranded DNA binding; single-stranded DNA helicase activity; ATP binding; DNA helicase activity
Biological process: DNA replication; DNA replication initiation; DNA strand elongation involved in DNA replication; double-strand break repair via break-induced replication; mitotic DNA replication initiation; regulation of DNA-templated DNA replication initiation; DNA metabolic process
Cellular component: chromosome, telomeric region; CMG complex; MCM complex; membrane; nucleolus; nucleus; perinuclear region of cytoplasm; alpha DNA polymerase:primase complex; nucleoplasm; chromosome; cytoplasm
Genetic constraint (gnomAD): Loss-of-function variants: 54 observed, 83.38 expected, observed/expected ratio (o/e) 0.65, 90% interval 0.52 to 0.81. The upper end of that interval is the gene's LOEUF score, 0.81, which puts it in group 3 of 6, group 1 being the genes least tolerant of losing a copy. Missense variants: 865 observed, 1,035 expected, observed/expected ratio (o/e) 0.84, 90% interval 0.79 to 0.88. Synonymous variants: 370 observed, 383.64 expected, observed/expected ratio (o/e) 0.96, 90% interval 0.88 to 1.05.
Homologues: Orthologues: chimpanzee MCM3 (99% identical), macaque MCM3 (99% identical), dog MCM3 (98% identical), rabbit MCM3 (97% identical), pig MCM3 (97% identical), guinea pig MCM3 (95% identical), rat Mcm3 (94% identical), mouse Mcm3 (93% identical), tropical clawed frog zmcm3 (80% identical), zebrafish mcm3 (75% identical), Drosophila melanogaster Mcm3 (63% identical), Caenorhabditis elegans mcm-3 (49% identical). Paralogues in human: MCM2 (30% identical), MCM6 (29% identical), MCM4 (29% identical), MCM5 (29% identical), MCM7 (28% identical), MCM9 (27% identical), MCM8 (23% identical), MCMDC2 (13% identical).
Diseases named in the same sentence as MCM3 in open-access papers:
MCM3 is named in the same sentence as 105 diseases in open-access papers, as found by Europe PMC text mining. Sharing a sentence is not in itself a finding about the gene and the disease. The quoted sentences say what the papers report.
breast cancer (16 papers, 2010 to 2025). A primary or metastatic malignant neoplasm involving the breast. "Subsequently, MCM3 expression was evaluated in the second cohort consisting of 218 postmenopausal patients with high-risk, early-stage, ER+ breast cancers, who had received adjuvant tamoxifen mono-therapy." (PMID 33398005, 2021). "Our results indicate that MCM3 may be a more robust prognostic marker, easy to assess by immunohistochemistry, and works in both low- and high-risk ER+ breast cancer patients." (PMID 33398005, 2021). "For instance, the expression patterns of conventional tumor markers, such as the proliferating cell nuclear antigen (PCNA) and the minichromosome maintenance protein 3 (MCM3) in breast cancer were found to be similar to those of KRT18." (PMID 36949761, 2023). "MCM2 and MCM3 have also been reported to have a role in DNA repair mechanisms in breast cancer, and these genes have also been reported as predictors of other NAC response predictive models." (PMID 35205629, 2022). "First, we evaluated MCM3 expression by Western blotting after treating ER+ breast cancer cells with CDK4/6i alone and in combination with endocrine therapy." (PMID 33398005, 2021). "We evaluated the mechanism by which minichromosome maintenance protein 3 (MCM3) influences endocrine resistance and its predictive/prognostic potential in ER+ breast cancer." (PMID 33398005, 2021). "The clinical relevance of MCM3 expression as a biomarker was demonstrated in primary ER+ breast cancers of 4 large well-characterized cohorts of ER+ breast cancer patients." (PMID 33398005, 2021). "This suggests that MCM3 expression is a more consistent and reliable marker of clinical outcome in ER + breast cancer patients than Ki67." (PMID 33398005, 2021). "We compared the prognostic potential of Ki67 with MCM3 in 4 different cohorts of ER+ breast cancer patients treated with anti-hormonal therapy." (PMID 33398005, 2021). "We discovered that ER+ breast cancer cells survive tamoxifen and letrozole treatments through upregulation of minichromosome maintenance proteins (MCMs), including MCM3, which are key molecules in the cell cycle and DNA replication." (PMID 33398005, 2021). "The MCM3 gene was shown to promote cell replication and reflect cancer cell proliferation in breast cancer." (PMID 34065619, 2021). "The first cohort consisted of postmenopausal patients with early ER+ breast cancers (n = 79) who received adjuvant tamoxifen mono-therapy for 5 years of which 68 had sufficient tumor tissue for MCM3 staining." (PMID 33398005, 2021). "In conclusion, our results showed increased expression of MCM3 in endocrine-resistant breast cancer cell lines, and that this upregulation plays a significant role in protecting cells against tamoxifen- or letrozole-mediated growth inhibition and apoptosis." (PMID 33398005, 2021). "We found that MCM2 and MCM3 expression were negatively correlated with patient OS in breast cancer and lung cancer." (PMID 28460433, 2017). "MCM3 upregulates the proliferation of MCF-7 breast cancer cells and H1299 lung cancer cells." (PMID 33816217, 2021). "Moreover, the expression of MCM3 is deregulated in several human malignancies, including lung cancer, colorectal cancer, liver cancer, breast cancer, ovarian cancer, and oral squamous cell carcinoma." (PMID 34671420, 2021). "Interestingly, patients with MCM3+ tumors also had a significantly shorter breast cancer-specific survival (BCSS) compared to patients with MCM3− tumors." (PMID 33398005, 2021). "To explore whether MCM expression levels were associated with clinical outcome of tamoxifen treatment, we evaluated MCM3 expression by immunohistochemistry in three independent cohorts ER+ breast cancer patients." (PMID 33398005, 2021).
breast cancer (continued). "In this study, quantitative proteomic analysis revealed upregulation of MCM3 in tamoxifen- and AI-resistant breast cancer cells and knockdown of MCM3 resensitized these cells to tamoxifen or letrozole and resulted in altered phosphorylation of cell cycle regulator proteins." (PMID 33398005, 2021). "Our study reveals a coordinated signaling network centered around MCM3 that limits response to endocrine therapy in ER+ breast cancer and identifies MCM3 as a clinically useful prognostic and predictive biomarker that allows personalized treatment of ER+ breast cancer patients." (PMID 33398005, 2021). "In breast cancer, MCM3 has been reported to be a better biomarker in prognosis than Ki67." (PMID 34859821, 2021). "MCM2 and MCM3 seem to have the most important role in several types of neoplasia, including alimentary system tumors, genitourinary system tumors, lung cancer, breast cancer, and meningioma." (PMID 25046975, 2014). "When a dose of Mcm3 was removed from mice of this genotype, lifespan was extended dramatically in both sexes as a consequence of delayed cancer onset, and the cancer spectrum shifted from lymphoma/thymoma towards mammary tumors." (PMID 20838603, 2010). "Importantly, MCM3 is overexpressed in some human cancers, including breast cancers." (PMID 35101047, 2022). "Taken together, the results suggest that MCM3, in addition to being a predictive marker of tamoxifen benefit in ER+ breast cancer, is a more consistent prognostic marker in ER+ breast cancer than Ki67, and may add information to clinical decision-making beyond that of Ki67." (PMID 33398005, 2021). "IHC assays revealed that MCM3 protein was remarkably upregulated in luminal breast cancer, HER2+ breast cancer, and TNBC tissues (p < 0.01), and MCM3 expression was highest in TNBC tissues." (PMID 41502508, 2025). "We evaluated the expression of MCM3 and AURKA by immunohistochemistry in metastatic lesions from ER+ advanced breast cancer patients treated with combined CDK4/6i and endocrine therapy (n = 86)." (PMID 33398005, 2021). "We found that CDK4/6i alone reduced MCM3 levels in both endocrine-sensitive (MCF7/S0.5) and -resistant (TamR-1, LetR-1, and FulvR-1) breast cancer cell lines." (PMID 33398005, 2021). "Next, we investigated whether MCM3 expression affects response to combined CDK4/6i and endocrine therapy in ER+ breast cancer cell lines." (PMID 33398005, 2021). "The MCM3 level was examined by immunohistochemistry in the Stockholm Tamoxifen (STO-3) trial from the Stockholm Breast Cancer Study Group randomizing postmenopausal lymph node-negative breast cancer patients to receive adjuvant tamoxifen versus not15." (PMID 33398005, 2021). "Mcm3 is overexpressed in most tumors in human studies, and MCM6 expression is positively correlated with cell proliferation, migration, invasion, and immune response in numerous cancer types, including breast cancer, hepatocellular carcinoma, lung cancer, and esophageal squamous cell carcinoma." (PMID 39272991, 2024). "Evaluation of MCM3 levels in primary tumors from four independent cohorts of breast cancer patients receiving adjuvant tamoxifen mono-therapy or no adjuvant treatment, including the Stockholm tamoxifen (STO-3) trial, showed MCM3 to be an independent prognostic marker adding information beyond Ki67." (PMID 33398005, 2021). "The clinical relevance of MCM3 levels was demonstrated by its strong correlation with RFS and OS in 4 independent cohorts consisting of 79, 218, 2305, and 683 early-stage, ER+ breast cancer patients receiving adjuvant tamoxifen or no adjuvant treatment." (PMID 33398005, 2021). "In addition, we evaluated MCM3 expression at the mRNA level in a large cohort (cohort 3) of ER+ breast cancer patients treated with endocrine therapy (n = 1802), ER+ patients who did not receive any systemic therapy (n = 503) as well as ER− breast cancer patients (n = 250)." (PMID 33398005, 2021).
melanoma (15 papers, 2006 to 2025). A malignant, usually aggressive tumor composed of atypical, neoplastic melanocytes. "In light of the observed inverse association between expression of MCM3 and RBM3 in primary melanoma, we also examined differences in survival according to combined categories of low and high MCM3 and RBM3 expression." (PMID 22805320, 2012). "In this study, we have demonstrated that high immunohistochemical expression of MCM3 is an independent predictor of an increased risk of recurrence and death from melanoma in a large, prospective, population-based cohort study." (PMID 22805320, 2012). "The poor prognostic effect of MCM3 overexpression was also shown in gliomas, thyroid carcinomas, melanoma, cutaneous T-cell lymphomas and oral squamous cell carcinomas." (PMID 34144903, 2022). "In the present study, MCM3 was found to be overexpressed in melanoma tissue compared with normal skin tissue." (PMID 34490114, 2021). "MCM3 was found to be more reliable prognosis biomarker than Ki-67 for malignant melanoma and salivary gland tumors." (PMID 34490114, 2021). "Increased level of MCM3 has also been observed in liver cancer, salivary gland tumors, prostate cancer, melanoma, and cervical squamous cell carcinoma." (PMID 34993142, 2021). "We then validated the transcriptional expression of key candidate genes such as CDKN1A (P21), GADD45A, and MCM3 after this compound treatment and knocking down Fyn expression in melanoma cells." (PMID 32565740, 2020). "Consistent with the sequencing results, RT-PCR confirmed that GADD45A and CDKN1A were upregulated in the Lj-1-60-treated group, while minichromosome maintenance 3 (MCM3) was downregulated in melanoma cells Sk-Mel-5 and Sk-Mel-28." (PMID 32565740, 2020). "Previous studies showed that high MCM3 expression is an independent biomarker for poor prognosis of malignant melanoma and epithelial ovarian cancer." (PMID 30363964, 2018). "Immunohistochemical MCM3 expression was examined in 224 incident cases of primary melanoma from the Malmö Diet and Cancer Study, previously analysed for RBM3 expression." (PMID 22805320, 2012). "In melanoma, gene expression analysis and immunohistochemical validation has uncovered MCM3 as a putative prognostic biomarker." (PMID 22805320, 2012). "The aim of the present study was to examine the associations of MCM3 expression with clinical outcome and RBM3 expression in a prospective, population-based cohort of melanoma." (PMID 22805320, 2012). "Similarly, we found elevated expression of MCM3 was related to worse prognosis in melanoma patients, which is consistent with the previous study, but the statistical significance was low." (PMID 34490114, 2021). "High expression of MCM3 has been reported in other types of neoplasia including papillary thyroid carcinoma, cervical squamous cell carcinoma, ameloblastoma and malignant melanoma." (PMID 32597491, 2020). "Thus, the potential value of MCM3 expression as a prognostic biomarker in thin melanomas merits further investigation in larger patient cohorts." (PMID 22805320, 2012). "The prognostic value of MCM3 expression in thin melanomas (≤ 1 mm; n = 137) was also examined." (PMID 22805320, 2012). "Moreover, we have demonstrated an inverse association between tumour-specific expression of MCM3 and the RBM3 protein, loss of which has previously been found to correlate with tumour progression and poor prognosis in melanoma." (PMID 22805320, 2012). "The findings from this prospective cohort study provide an independent validation of MCM3 expression as a biomarker of poor prognosis in malignant melanoma, also in the category of thin melanomas, which may be of particular clinical relevance." (PMID 22805320, 2012). "Moreover, the inverse association and prognostic impact of MCM3 and RBM3 expression indicate a possible interaction of these proteins in melanoma progression, the functional basis for which merits further study." (PMID 22805320, 2012).
melanoma (continued). "Of the genes correlated with shorter survival, some were already known to be over-expressed in different types of cancer, such as MCM3, BCHE, and some have previously been implicated in melanoma progression, like CSPG4 and Cx26 or, more generally, associated with tumor invasiveness, like ADAMTS5." (PMID 17129373, 2006). "A similar study on BRAFV600E inhibitor-addicted melanoma cells revealed downregulation of MCM2, MCM3 and MCM5 upon drug withdrawal in correlation with reduced cell viability ensuing from discontinued drug treatment." (PMID 37106808, 2023). "In malignant melanoma, gene expression analysis and independent immunohistochemical validation have uncovered several MCM family members, i.e. MCM3, MCM4 and MCM6 as biomarkers of poor prognosis." (PMID 22805320, 2012). "Kaplan Meier analysis, the log rank test, and univariable and multivariable Cox proportional hazards modelling were used to assess the impact of MCM3 expression on disease-free survival (DFS) and melanoma-specific survival (MSS)." (PMID 22805320, 2012). "The TIMER analysis showed that MCM3 was closely correlated with B cells and CD4+ and CD8+ T cells, which may provide a new approach to immunotherapy for melanoma." (PMID 34490114, 2021). "We additionally confirmed the expression with mRNA levels of key genes after treatment with lj-1-59 in melanoma cells, which indicated that P21, BBC3, SESN2 and GADD45A expression were significantly upregulated, while MCM2, MCM3, MCM4, MCM7 and PKMYT1 were significantly downregulated." (PMID 32021565, 2020). "In previous study, MCM2, MCM3 and MCM4 were dysregulated in malignant salivary gland tumours, gastric cardiac cancer, thyroid malignancy, non-small cell lung cancer, malignant melanoma, colon cancer, promyelocytic leukemia, cervical squamous cell carcinoma." (PMID 24386425, 2013). "Longitudinal analysis did not reveal an altered expression of MCM3 in metastatic compared to primary melanoma, in contrast to RBM3, that was found to be downregulated in metastatic melanoma in two independent studies, including the present cohort." (PMID 22805320, 2012). "While we are not aware of any other validatory studies on the prognostic value of MCM3 expression in melanoma, a recent study failed to confirm the prognostic value of MCM4 in a consecutive cohort of nodular melanoma (n = 220)." (PMID 22805320, 2012). "In contrast to MCM3, however, Ki67 expression was not prognostic in the full cohort in our previous study, only in male melanoma." (PMID 22805320, 2012). "Notably, none of the patients with melanomas lacking MCM3 expression had recurrent disease or died from melanoma." (PMID 22805320, 2012).
colorectal cancer (14 papers, 2016 to 2025). A primary or metastatic malignant neoplasm that affects the colon or rectum. "KIF14, KIF18B, KIF23, KIF4A, KNTC1, NCAPG2, and MCM3 regulate chromosomal integrity, mitotic spindle formation, and DNA replication, processes that are frequently dysregulated in colorectal cancer." (PMID 40405535, 2025). "Zhou H. et.al found that MCM3 was overexpressed in colorectal cancer cell lines and down-regulation inhibited proliferation, migration, invasion and promoted apoptosis." (PMID 38200573, 2024). "It was also previously reported that elevated expression of MCM3 (another member of MCMs) promoted G1/S cell cycle progression, proliferation, invasion and migration in colorectal cancer." (PMID 35813483, 2022). "CCLE analysis revealed that the expression of MCM3 in colorectal cancer ranked 15th among all types of cancer." (PMID 32597491, 2020). "Taken together, according to our microarray findings, BTF3 seems to be association with MAD2L2, MCM3, and PLK1 through regulatory effects in different stages of mitosis, which affect proliferation and cell cycle of colorectal cancer cells." (PMID 31263147, 2019). "It has been shown that transfection of BTF3 siRNA into HCT116 cells reduces cell viability, induces apoptosis, blocks the cell cycle, and attenuates tumorigenicity of colorectal cancer cells by decreasing the activities of MAD2L2, MCM3, and PLK147." (PMID 38203709, 2023). "To further validate the RLBPs expression in two clusters, we performed immunohistochemistry (IHC) of MCM3 and MCM5 in colorectal cancer tissues." (PMID 36428700, 2022). "In conclusion, BTF3 is positively related to CRC and BTF3-siRNA attenuated the tumorigenicity of colorectal cancer cells via MAD2L2, MCM3 and PLK1 activity reduction." (PMID 31263147, 2019). "Moreover, inhibition of MCM3 or MCM2, one of the other MCMs members, suppresses transition of G1 to S phase in colorectal cancer or lung cancer cells." (PMID 37817427, 2023).